STAT1 (signal transducer and activator of transcription 1)
Diseases named in the same sentence as STAT1 in open-access papers (continued):
Sharing a sentence is not in itself a finding about the gene and the disease.
progeria (2 papers, 2022 to 2025). "Applying these stricter standards, three of the genes that are differentially expressed in aging and progeria (TFPI, STAT1, IGFBP2) appear to be associated with changes in protein expression." (PMID 36289702, 2022). "In progeria, STAT1 has been shown to be involved in an interferon (IFN)-like response upon progerin-induced replication stress." (PMID 36289702, 2022). "After additionally analyzing aging- and progeria-related proteomics analyses, the importance of STAT1, which is differentially expressed in both comparisons (nonagenarians and healthy children and HGPS patients and healthy children) and in proteomics analysis, became apparent." (PMID 36289702, 2022). "To evaluate the status of STAT1 and STAT3 activation in the LmnaG609G/G609G mouse model, we performed western blot analyses on multiple tissues commonly affected by progeria." (PMID 40429989, 2025).
prostate adenocarcinoma (2 papers, 2019 to 2020). "Additionally, we examined the efficacy of the IL-27 cytokines modified at the C-terminus in a STAT1-luc reporter assay, where co-transfection of IL-27ns vector augmented the STAT1 activity in both TC2R and Ras/Myc murine prostate adenocarcinoma cells (RM1) cell lines (p < 0.05)." (PMID 32046108, 2020).
Pruritus (2 papers, 2017 to 2022). Pruritus is an itch or a sensation that makes a person want to scratch. "STAT1, IL2, and NF-κB are in the toll-like receptor signaling pathway and are related to pruritus pathogenesis." (PMID 28869563, 2017).
red cell aplasia (2 papers, 2022 to 2023). "According to the whole-exome sequencing (WES), the patient was genetically mutated in STAT1 GOF (c.854A>G, p.Q285R), and bone marrow biopsy suggested pure red cell aplasia (PRCA)." (PMID 36105803, 2022).
Respiratory syncytial virus infection (2 papers, 2015 to 2025). "Respiratory syncytial virus infection could induce the phosphorylation of Stat1 at 24 hpi, nevertheless the presence of PHPS1 did not change Stat1 phosphorylation." (PMID 26119280, 2015).
salmonellosis (2 papers, 2007 to 2013). Infections with bacteria of the genus salmonella. "Furthermore, a STAT-1 defect increases the risk of invasive salmonellosis in humans." (PMID 23349666, 2013).
synovitis (2 papers, 2022). Inflammation of a synovial membrane. "Our results show significant correlation between synovial IL-6, JAK2, STAT1; blood IL-6 and lympho-myeloid synovitis." (PMID 36465908, 2022). "Extending the investigation of STAT1 and STAT3 cytokine signalling to wild‐type, Il6−/− and Il27ra−/− mice with antigen‐induced arthritis, studies show that these mice develop joint disease resembling the heterogeneous features of synovitis commonly seen in humans with rheumatoid arthritis." (PMID 34618359, 2022).
T-cell deficiency (2 papers, 2019 to 2021). "Although NOS2 expression is characteristically elicited by IFNγ-induced activation of STAT1-dependent gene transcription, expression of this cytokine was not affected by ChAT T-cell deficiency." (PMID 30973939, 2019).
tendinopathy (2 papers, 2017 to 2022). "STAT1 and STAT3, members of the cytoplasmic family of transcription-factor (STAT) signal-transducers and activators, have been associated with inflammatory pathologies, including tendinopathy." (PMID 36499497, 2022). "Incubation of tendon-derived stromal cells from both healthy volunteers and patients with tendinopathy in SPM including 15-epi-LXA4 or MaR1 induced further release of proresolving mediators and counter regulated the expression of pro-inflammatory molecules including PGE2, IL-6, STAT-1 and PDPN." (PMID 28887458, 2017).
viral hepatitis (2 papers, 2017 to 2020). An acute or chronic inflammation of the liver parenchyma caused by viruses. "Functional dichotomy of NK cells in viral hepatitis was caused by two different signaling, phosphorylated STAT1 (pSTAT1) related to cytotoxicity and phosphorylated STAT4 (pSTAT4) related to cytokine production." (PMID 28328926, 2017).
abscesses (1 paper, 2017). "Although the pathogenic microorganism could not be isolated, invasive deep-seated abscesses are uncommon for patients with STAT1 GOF mutations." (PMID 28348565, 2017).
Acidosis (1 paper, 2023). Abnormal acid accumulation or depletion of base. "Acidosis-induced PD-L1 expression was mediated by increased STAT1 activity, which relied on the efficient translation of the Stat1 mRNA by elF4F." (PMID 38102680, 2023).
acute liver failure (1 paper, 2016). Rapid deterioration of liver function causing encephalopathy and coagulopathy. "Consistent with previously published data, transplantation of 2 × 105 or 4 × 105 mouse hepatocytes from STAT1−/− mice rescued Alb-uPA SCID/beige mice from acute liver failure and resulted in successive weight gain (data not shown)." (PMID 27834208, 2016).
acute myelomonocytic leukemia (1 paper, 2025). "SFX-01 also induced STAT1 phosphorylation as well as loss of cyclin D1 expression in the human acute myelomonocytic leukemia GDM-1 cell line that expresses an activating Shp2 mutation associated with JMML and NS." (PMID 40640547, 2025).
adenosquamous carcinoma (1 paper, 2025). A carcinoma composed of malignant glandular cells and malignant squamous cells. "Despite the broad activation of JAK/STAT signaling cascades and low-grade histopathological features of these adenosquamous carcinomas, the TSG101-induced tumors lacked active STAT1, which is a suggested tumor suppressor." (PMID 40624726, 2025).
adenovirus infection (1 paper, 2025). "It is crucial to emphasize that the lethal HAdV-4 infection model in STAT1+/− mice better recapitulates the clinical scenario of severe adenovirus infection in immunodeficient patients, who are most susceptible to adverse outcomes." (PMID 41441659, 2025).
adrenocortical carcinoma (1 paper, 2025). "Our matched tumor-normal analysis across 19 tissue pairs demonstrated that adrenocortical carcinoma (ACC) exhibited significantly reduced STAT1 dual-isoform expression compared to normal adrenal tissue (p < 0.05)." (PMID 40849492, 2025).
adult-onset Still disease (1 paper, 2022). A rare inflammatory multisystem disorder characterized clinically by fever of unknown origin, arthralgia or arthritis, hyperleucocytosis, and typical skin rash. "To explore the association between anti-IFN-γ autoantibodies and OIs in patients with adult-onset Still's disease (AOSD), we aimed to examine the ability of these autoantibodies to blockade signal transducer and activator of transcription (STAT1)-phosphorylation and chemokines production." (PMID 36698819, 2022).
age (1 paper, 2018). A temporal measurement of the time period elapsed since an identifiable point in the life cycle of an organism. "Further elucidation of the roles of STAT1 and STAT2 may enable development of chemotherapeutic agents to prevent aging and/or age-related pathologies." (PMID 30455980, 2018).
alveolitis (1 paper, 2020). "Compared with the BLM group, the degree of alveolitis and fibrosis improved significantly, and the expression of p-JAK1 and p-STAT1 decreased; conversely, the expression of SOCS3 increased in the treatment group." (PMID 32908556, 2020).
anal squamous cell carcinoma (1 paper, 2021). A squamous cell carcinoma (SCC) arising from the anal canal or the anal margin (perianal skin). "However, it is notable that loss of STAT1, JAK2, and CD274 was detected in a patient with HPV18-positive anal squamous cell carcinoma who did not benefit from treatment." (PMID 34446728, 2021).
anaphylaxis (1 paper, 2019). An acute hypersensitivity reaction that occurs from exposure to an allergen. "Our findings that Stat1−/− mice showed normal systemic anaphylaxis and that the administration of a Stat3 inhibitor in a Stat1−/− but not WT background caused the exacerbation of anaphylaxis strongly suggested that Stat1 and Stat3 function redundantly in this process." (PMID 31730616, 2019).
aortic aneurysm (1 paper, 2023). A ruptured aneurysm located in the wall of the proximal portion of the descending aorta proceeding from the arch of the aorta. "Furthermore, the interaction between platelets and neutrophils also represents a driving force in various vascular diseases, such as aortic aneurysm (AA), and large vessel aneurysms are one of the unexplained symptoms of STAT1 GOF CMC, present in approximately 6 % of patients." (PMID 37358695, 2023).
Arrhythmogenic right ventricular dysplasia (1 paper, 2014). "STAT1 and STAT3, which we also associate with arrhythmogenic right ventricular dysplasia, were recently found to be elevated in mice with sustained atrial fibrillation." (PMID 24516403, 2014).
Atherosclerotic lesion (1 paper, 2025). A lesion associated with atherosclerosis, a multifactorial and multipart progressive disease manifested by the focal development within the arterial wall of lesions, that ranges from the development of a fatty streak, plaque progression, and plaque disruption. "Moreover, identification of a subset of 24 MØ-specific STAT1-dependent genes, commonly expressed in human and mouse atherosclerotic lesions, could represent a novel gene signature to monitor plaque progression during human atherosclerotic disease." (PMID 40607379, 2025).
BK-virus nephropathy (1 paper, 2021). "The expression of STAT1 has been associated with inflammatory processes in KT related to ischemia-reperfusion damage and BK virus nephropathy." (PMID 34975915, 2021).
bladder tumors (1 paper, 2017). "STAT1 the intermediate signal in viral defense pathway was frequently downregulated in bladder tumors." (PMID 29242529, 2017).
bone marrow failure syndrome (1 paper, 2024). "In addition, we recapitulate the characteristics of the six CMC SAA cases that have been reported so far and discuss the significance of STAT1 GOF pathogenic variants and other STAT1 signaling derangements in the context of these specific types of bone marrow failure syndromes." (PMID 39114664, 2024).
brain glioma (1 paper, 2023). A malignant glioma that involves the brain. "Studies have shown that high expression of signal transducer and activator of transcription 1 (STAT1) in brain gliomas is associated with poorer OS in patients." (PMID 37837543, 2023).
brucellosis (1 paper, 2024). Brucellosis is a bacterial infection that spreads from animals to people via unpasteurized dairy products or by exposure to contaminated animal products or infected animals. "In line with this, the enrichment of genes linked to the ‘interferon‐gamma response’ pathway (e.g., STAT1, IFNG, IRF1, B2M, GAPDH) was also consistently observed in brucellosis patients." (PMID 39135683, 2024).
Cachexia (1 paper, 2024). Severe weight loss, wasting of muscle, loss of appetite, and general debility related to a chronic disease. "In summary, our data demonstrate that Epsti1 plays a critical role in muscle regeneration and the prevention of cachexia-induced muscle wasting through limiting inflammatory responses by modulation of the VCP/STAT1 axis." (PMID 38993551, 2024).
carditis (1 paper, 2014). "Fundamental differences between strains have been reported previously in Lyme carditis studies comparing the effect of Stat1 and Ccr2 deficiencies on carditis-susceptible and carditis-resistant mouse strains." (PMID 24967703, 2014).
chondrosarcoma (1 paper, 2022). A malignant cartilaginous matrix-producing mesenchymal neoplasm arising from the bone and soft tissue.
cicatricial alopecia (1 paper, 2024). Scarring hair loss, also known as cicatricial alopecia, is the loss of hair which is accompanied with scarring. "We could readily visualize the phosphorylation of STAT1 and the upregulation of MHC-I on epidermal cells from patients under EGFR-inhibitor therapy and the pSTAT1 signature in patients with cicatricial alopecia." (PMID 39521937, 2024). "Active STAT1 signaling could be readily detected in patient samples during EGFR-inhibitor treatment and in different types of cicatricial alopecia." (PMID 39521937, 2024).
colon adenoma (1 paper, 2025). An adenoma that arises from the colon. "Taken together, the transcriptomic results indicate that there is a marked anti-oncogenic effect of TTI-101 on the CRC transcriptome mediated largely by its targeting of STAT3 and STAT1 in the colons of TTI-101-treated AOM-DSS mice, which helps to explain its ability to reduce colon adenomas." (PMID 41226842, 2025).
congenital heart disease (1 paper, 2025). A heart disease that is present at birth. "One of our patients had congenital heart disease, similarly to what has been previously reported in another STAT1 LOF patient." (PMID 40881691, 2025).
congestive heart failure (1 paper, 2023). Failure of the heart to pump a sufficient amount of blood to meet the needs of the body tissues, resulting in tissue congestion and edema. "Furthermore, DisGeNET data show that two genes, including STAT1 and CCND1, have not been associated with IDCM, but STAT1 is related to congestive heart failure." (PMID 37372424, 2023).
corneal infection (1 paper, 2011). A viral or bacterial infectious process affecting the cornea. "Here we examined herpes simplex virus type 1 (HSV-1) pathogenesis in Stat1−/− mice and in IFNαßγR−/− mice following corneal infection and bioluminescent imaging." (PMID 21915277, 2011).
cutaneous sarcoidosis (1 paper, 2023). "The implication of IFN-γ on Mɸ in human skin is underlined by its effects on Mɸ immunologic reprofiling: in cutaneous sarcoidosis, IFN-γ-related expression of downstream translational targets includes STAT1, CEBPB, FN1, TREM1, CXCL9, CXCL10, IL-6, and others." (PMID 36902053, 2023).
cystic kidneys (1 paper, 2026). "We observed that the overexpression of CFB in cystic kidneys was associated with increased Janus kinase 2 (JAK2)/signal transducer and activator of transcription 1 (STAT1) activity and enhanced expression of the polycystin-1 C-terminal tail (PC1-CTT)." (PMID 41431718, 2026).
cystitis (1 paper, 2021). Inflammation of the urinary bladder. "Previously, we verified that glucose promotes UPEC-induced cystitis and invasion into uroepithelial epithelial cells by activating TLR-4-mediated UPEC infection and JAK/STAT1-dependent pathways." (PMID 34946023, 2021).
demyelinating disease (1 paper, 2023). A broad group of disorders that affect the myelin sheaths that cover the neurons. "Our findings uncover a novel function of Stat1 to regulate SC differentiation and myelination, providing a candidate molecular target for clinical interventions such as drug design in demyelinating diseases." (PMID 37365519, 2023). "In summary, our findings uncover a novel function of Stat1 to regulate SC differentiation and myelination, providing a candidate molecule for clinical intervention in demyelinating diseases such as MS." (PMID 37365519, 2023). "Our findings demonstrate that Stat1 regulates SC differentiation to control myelinogenic programs and repair, uncover a novel function of Stat1, providing a candidate molecule for clinical intervention in demyelinating diseases." (PMID 37365519, 2023).
diarrheal disease (1 paper, 2016). The condition of having at least three loose or liquid bowel movements each day. "In addition, in the current study weight loss and the degree of diarrheal disease were not substantially enhanced in Ifnlr1-/- and/or Stat1-/- mice when compared to WT suckling mice." (PMID 27128797, 2016). "However, diarrhea was moderately prolonged in the EW-RV-infected Stat1-/- mice, suggesting that IFN signaling may affect the duration of murine RV-associated diarrheal disease." (PMID 27128797, 2016).
disseminated tuberculosis (1 paper, 2022). "In particular, a novel splice site mutation c.373–2A>C in STAT1 gene was found and functionally confirmed in a patient with disseminated tuberculosis." (PMID 36338958, 2022).
Down syndrome (1 paper, 2025). "The biomarkers most frequently analyzed in studies of Down syndrome were IL-10, TNF-alpha, IL-1 beta, IL-4, IFN-gamma, and the genes STAT1, STAT3, and SOCS3, all of which are involved in the regulation of the immune response and periodontal inflammation." (PMID 41462866, 2025).
ductal breast carcinoma (1 paper, 2017). "In Curtis's dataset, overexpression of STAT1 was found in all types of BC compared with normal samples, medullary BC with fold change = 6.511, invasive ductal BC with fold change = 3.025, invasive lobular BC with fold change = 2.223 and ductal breast carcinoma in Situ with fold change = 2.673." (PMID 28422733, 2017).
Dupuytren’s disease (1 paper, 2020). "By chromatin immunoprecipitation (ChIP), we also show enriched signal transducer and activator of transcription 1 (STAT1) binding at the IL-13Rα1 site that drive the enhanced fibrotic response in Dupuytren’s disease." (PMID 32695877, 2020).
esophageal tumor (1 paper, 2025). "We speculate that EGF likely upregulates the expression of apoptosis-related genes downstream of the IFN-γ/STAT1 pathway, thereby facilitating the apoptosis of esophageal tumor cells." (PMID 40909948, 2025).
esophagitis (1 paper, 2020). An acute or chronic inflammatory disease affecting the esophageal wall. "We suggest that patients with severe recurrent aphthous stomatitis and esophagitis should be evaluated for STAT1 GOF mutation." (PMID 32547544, 2020).
Ewing sarcoma (1 paper, 2014). A small round cell tumor that lacks morphologic, immunohistochemical, and electron microscopic evidence of neuroectodermal differentiation. "Selective IFN-β-induced activation of Jak1 and higher STAT-1 phosphorylation upon IFN-β vs. IFN-α treatment were observed in both human myocardial fibroblasts and vascular endothelial cells, and a superior antiproliferative effect of IFN-β over IFN-α was shown in Ewing’s sarcoma cells in vitro." (PMID 24472094, 2014).
extrapulmonary tuberculosis (1 paper, 2021). A tuberculosis that occurs at body sites other than the lung. "STAT1 involves M1 macrophage polarization, which may affect osteolysis and bone remodeling of extrapulmonary tuberculosis." (PMID 35127768, 2021).
Facioscapulohumeral dystrophy (1 paper, 2023). Facioscapulohumeral muscular dystrophy (FSHD) is characterized by progressive muscle weakness with focal involvement of the facial, shoulder and limb muscles. "Conservation of interferon-stimulated gene (ISG) repression in facioscapulohumeral dystrophy (FSHD) myoblasts and ISG repression and STAT1 interaction by mouse Dux." (PMID 37092726, 2023).
familial Mediterranean fever (1 paper, 2024). Familial Mediterranean fever (FMF) is an autoinflammatory disorder characterized by recurrent short episodes of fever and serositis resulting in pain in the abdomen, chest, joints and muscles. "Although most patients recover from myocarditis, MEFV mutations in familial mediterranean fever (FMF) or STAT1 gain-of-function mutations, for example, may contribute to myocardial injury due to aberrant host immunity." (PMID 38485795, 2024).
focal segmental glomerulosclerosis (1 paper, 2025). A renal disorder characterized by sclerotic lesions in the glomeruli. "In focal segmental glomerulosclerosis (FSGS), the JAK–STAT signaling pathway is activated, with increased phosphorylation of STAT1 and STAT3 in both the glomerulus and renal tubulointerstitium." (PMID 40384344, 2025).
folliculitis (1 paper, 2024). Inflammation of the hair follicles. "Confirming these transcriptomic data, phosphorylated STAT1 was elevated on protein level in the hair follicle and epidermis of biopsies from folliculitis decalvans (FD), frontal fibrosing alopecia (FFA) and LPP patients (E and EV5B)." (PMID 39521937, 2024).